EGFR (epidermal growth factor receptor)
Diseases named in the same sentence as EGFR in open-access papers (continued):
Sharing a sentence is not in itself a finding about the gene and the disease.
tumor (continued). "To overcome these limitations, we introduced deep learning models capable of automatically learning EGFR‐related tumor characteristics, eliminating the need for manual segmentation." (PMID 41263395, 2025). "Senescent endothelial cells secrete exosomal SLC1A5, which is taken up by tumor cells and suppresses ferroptosis in tumor cells via the EGFR/SRC/YAP1/GPX4 pathway, thereby promoting gastric cancer progression." (PMID 40919170, 2025). "In the EGFRmut model, 75% of the animals (six out of eight) receiving combination treatment remained tumor progression-free almost 3 months after the EGFR drug was stopped, including 25% (two animals) with complete regression." (PMID 39699269, 2025). "Anti-EGFR aptamers were conjugated at the surface via electrostatic adsorption, allowing for enhanced accumulation at tumor sites." (PMID 39940134, 2025). "Despite prolonged disease control and high tumor response rates, all patients eventually progress on EGFR-TKIs treatment." (PMID 41383506, 2025). "Epigenomics highlighted the impact of DNA methylation and histone modifications on EGFR and its downstream genes, whereas metabolomics demonstrated shifts in metabolic patterns essential for tumor growth." (PMID 40486879, 2025). "The present case report highlights a patient whose tumor underwent transformation to SCLC after developing resistance to an EGFR-TKI treatment." (PMID 41001033, 2025). "High EUDAL expression facilitates sustained EGFR phosphorylation in hypoxic tumor cells and leads to autophagy-related drug resistance." (PMID 40940319, 2025). "Currently, preclinical and clinical studies are investigating targeted fluorophores that bind to specific tumor epitopes, such as integrins or surface receptors (e.g., EGFR or VEGF)." (PMID 41094345, 2025). "In conclusion, we propose that high expression of fDEGs characterizes primary HNSCC and recurrences with a dependency from EGFR-activity subtype-driven tumor progression." (PMID 40121428, 2025). "AFM24 is a tetravalent bispecific antibody in which the anti-EGFR scFv is fused to the c-terminus of the anti-CD16a antibody via a connector, which mediates the killing of tumor cells by NK cells in an EGFR-dependent manner." (PMID 40510353, 2025). "EGFR-BBζ CAR-T-cell therapy resulted in minimal tumor growth control, while tumor growth in the EGFR-BBζ + CD2 treatment group was markedly suppressed." (PMID 40615696, 2025). "Other forms of TRTs include peptide receptor radionuclide therapy (PRRT), nanoparticles, and antibody-based radionuclide therapy targeting tumor-specific antigens, including EGFR and EGFRvIII." (PMID 40868217, 2025). "Tumor-associated antigens like MSLN, CEA, EGFR, ROR1, and c-Met are overexpressed in many solid tumors but often show low-level expression in normal tissues." (PMID 40969260, 2025). "For example, the bispecific Nanofitins B10-B11 selectively recognizes tumor cells co-expressing high levels of EGFR and PD-L1." (PMID 41155373, 2025). "The indirect and significant enhancement of tumor immunity by EGFR‐TKIs has been shown to reverse the immunosuppressive TME, making the combination of targeted and immunotherapy feasible." (PMID 40859900, 2025). "Sorafenib hinders the inhibition of tyrosine kinase receptors such as VEGFR-2, VEGFR-3, PDGFR-β, EGFR, c-Kit, and Flt3, which ultimately impedes the proliferation of tumor cells and angiogenesis." (PMID 41050183, 2025). "At the same time, the long latency of EGFR-mutant cancers provides a wide time window for tumor early detection." (PMID 40161734, 2025). "EGFR, a well-established therapeutic target in tumor progression, is amplified in 80–90% of OSCC cases and linked to poor outcomes." (PMID 40362183, 2025).
tumor (continued). "As a result, it was observed that let-7a miRNA inhibits tumor growth by interfering with the EGFR signaling pathway." (PMID 40297849, 2025). "Inhibits FAK and Src kinases.Reduces tumor cell proliferation and induces apoptosis.Inhibits EGFR and Src/NF-κB/survivin signaling pathways." (PMID 41211420, 2025). "Since F9H4 does not block CD16a, it promotes NK cell-mediated ADCC and inhibits tumor growth in vivo in the context of co-administration with EGFR antibodies, which served here, in this study, as tumor antigen-targeting antibodies." (PMID 41219228, 2025). "By disrupting EGFR signalingpathways, 1,4-thiazepine derivatives can reduce tumor growth and promoteapoptosis, offering hope for improved treatment options with fewerside effects and enhanced efficacy against resistant cancer strains." (PMID 39829567, 2025). "As a result of the interaction of hyaluronic acid with CD44, EGFR-mediated pathways are activated, leading to tumor cell growth, tumor cell migration, and chemotherapy resistance in solid cancers." (PMID 40558504, 2025). "Targeting AREG has emerged as a promising strategy to overcome EGFR inhibitor resistance and suppress tumor progression across various cancer types." (PMID 40725192, 2025). "In vivo studies have demonstrated that blocking the HGF-MET axis can resensitize tumor cells to EGFR inhibitors and suppress relapse in lung cancer models." (PMID 40894234, 2025). "Pretreatment and post‐treatment resistant tumor samples from EGFR‐mutant or ALK‐positive patients demonstrate that SCLC transformation is one of the resistance mechanisms leading to tumor histological changes and independence from the original signaling axis." (PMID 41415713, 2025). "At the cut-off value of ≥5% of tumour cells with immunostaining, 46% (37/80) of the cases were wt-EGFR positive, with predominant intensity and cellular location of the staining being mostly 2+ (28%) and cytoplasmic (41%)." (PMID 40227788, 2025). "They offer critical support for analyzing gene expression changes linked to EGFR-TKI resistance and tumor microenvironment heterogeneity, paving the way for a deeper understanding of the mechanisms underlying the onset and progression of NSCLC." (PMID 40003951, 2025). "C1GalT1 modulates O‐glycosylation of the epidermal growth factor receptor, enhancing ligand‐binding affinity and downstream signaling, which promotes tumor progression." (PMID 40548474, 2025). "Meanwhile, EGFR plays a promotional role in tumor angiogenesis, which provides nutrients for tumor cell growth and accelerates tumor cell invasion and metastasis." (PMID 40230723, 2025). "Among these, 14-3-3ε—implicated in tumor invasiveness and metastasis—and PDCD6IP/ALIX—a key regulator of EGFR activity and immune checkpoint trafficking—were also validated by Western blot analysis." (PMID 41441336, 2025). "EGFR, frequently overexpressed or mutated in GBM, particularly in the EGFRvIII variant, is associated with aggressive tumor behavior and poor survival outcomes, although therapies targeting EGFR have had limited success." (PMID 40223032, 2025). "Targeted therapy for cSCC primarily relies on EGFR inhibitors (such as cetuximab), which act by blocking EGFR-mediated Tumor Cells proliferation signaling." (PMID 41333481, 2025). "In OSCC, Dio suppresses the binding of EGFR to the AT-rich sequences in the survivin promoter, significantly downregulating survivin expression and thereby inducing tumor cell apoptosis." (PMID 40391080, 2025). "Its genetic or pharmacologic inhibition suppresses KRAS- or epidermal growth factor receptor (EGFR)-mutant tumor growth." (PMID 41294748, 2025). "In EGFR patients, a poor response to EGFR-TKIs and rapid tumor progression suggest SCLC transformation." (PMID 40507907, 2025). "This study investigated the potential of a novel combination therapy using allogeneic natural killer (NK) cells and cetuximab, an anti-epidermal growth factor receptor monoclonal antibody, to enhance anti-tumor efficacy in HNSCC." (PMID 40063100, 2025).
tumor (continued). "Previous studies have suggested that EGFR-independent mechanisms are more important and common in osimertinib resistance owing to tumour heterogeneity." (PMID 40634956, 2025). "Regarding the efficacy of EGFR‐targeted cLNPs, a significantly inhibited tumor growth by 90% was observed in T‐sgSOX2‐cLNPs (T‐sgSOX2) compared to I‐sgNC‐cLNPs (I‐sgSOX2) treated mice." (PMID 39736115, 2025). "A subsequent lung biopsy revealed synaptophysin-positive SCLC harboring the same EGFR exon 19 deletion (L747-P753insQ) as the original tumor." (PMID 41516316, 2025). "The immunosuppressive tumor microenvironment (TME) following EGFR-TKI therapy has been proved to significantly affected the effectiveness of ICIs." (PMID 40510028, 2025). "Studies have shown that EGFR mutations, BRAF mutations, and changes in the tumor microenvironment were closely associated with cetuximab resistance." (PMID 40959565, 2025). "These modified exosomes have demonstrated the ability to induce a strong cellular immune response against EGFR‐positive TNBC tumours." (PMID 40032646, 2025). "Afatinib, a tyrosine kinase inhibitor (TKI) of the epidermal growth factor receptor (EGFR) family, prevents tumor growth and lymphangiogenesis via inhibiting VEGF-C secretion in the xenograft mouse model of NSCLC." (PMID 41511312, 2025). "EGFR (Epidermal Growth Factor Receptor) amplification favours tumour neoangiogenesis and accelerates proangiogenetic growth factors." (PMID 40870498, 2025). "The IVIS image and gross image demonstrated that mice in the EGFR downregulation group exhibited a significantly smaller tumor volume compared to the control group." (PMID 40162859, 2025). "Because it inhibits apoptosis, promotes angiogenesis, inhibits cellular proliferation, and promotes metastasis, EGFR activation contributes to malignant transformation and tumor growth." (PMID 41304988, 2025). "Targeting CMTM6 restores EGFR degradation, suppresses tumor growth, and confers therapeutic benefit in both CDX and PDX models, offering a promising strategy against TKI‐resistant NSCLC." (PMID 40521789, 2025). "Tumor cells can produce soluble and truncated EGFR isoforms that reduce antibody accessibility or function as ligand/antibody decoys." (PMID 41465349, 2025). "Targeting tyrosine kinases in CSCs using EGFR-targeted agents such as cetuximab and erlotinib is moderately effective at arresting tumor progression and the differentiation of OSCC subpopulations." (PMID 40678631, 2025). "Emerging evidence has demonstrated that tumor hypoxia can increase EGFR expression by promoting its transcription and protein synthesis." (PMID 40940319, 2025). "In EGFR wild-type cell lines (A549 and H1299), EGFR ablation significantly inhibited cell proliferation, migration and tumor formation." (PMID 39790707, 2025). "EGFR activation regulates tumor cell behavior through downstream signaling pathways such as extracellular signal‐regulated kinase and p38 MAPK." (PMID 40347011, 2025). "The Response Evaluation Criteria for Solid Tumours (RECIST 1.1) provides an objective, standardized method for assessing the efficacy of EGFR-TKIs, and requires the visual assessment of the tumor size based on radiological imaging." (PMID 40438144, 2025). "Having determined the pivotal role of EGFR in the tumor promotion of MMP-28, we aimed to elucidate the mechanism by which MMP-28 regulated EGFR." (PMID 39994761, 2025). "The EGFR-mutant group exhibited a significantly larger tumor surface area compared to the wild-type group (P = 0.043)." (PMID 41244899, 2025). "In lung adenocarcinomas with EGFR mutations, CD1C+ dendritic cells are increased, and tumor‐associated macrophages display tumor‐promoting functions with significant heterogeneity." (PMID 40062730, 2025). "Retrospective patient studies suggest otherwise, but because of the instability of pAKT in fixed tumour tissue, prospective studies investigating pAKT activity upon treatment with EGFR inhibitors would be useful." (PMID 40615716, 2025).
tumor (continued). "Clinically, high NOX4 and IL-8 correlate with poorer responses to anti-PD-L1 therapy, while dual inhibition of NOX4 (with GKT137831) and EGFR has shown enhanced tumor suppression in mouse xenograft models." (PMID 39941826, 2025). "Directing treatment against a dominant clonal neoantigen can additionally lead to tumor resistance via neoantigen loss, as illustrated in a case of EGFR-mutated NSCLC that lost the EGFR driver mutation in response to an EGFR neopeptide vaccine." (PMID 40149360, 2025). "While tumor tissue has been considered the gold standard for this testing, adequate material for EGFR molecular study cannot be obtained in up to 30 % of patients." (PMID 40977812, 2025). "Cetuximab-conjugated gold nanoparticles can increase EGFR endocytosis and degradation to decrease tumor growth." (PMID 40777019, 2025). "To further confirm the epithelial identity of the EGFR-low expressing cells, we co-stained tumors with epithelial cytokeratin 7 and EGFR and found subpopulations of the tumor expressing the epithelial marker but having low expression of EGFR." (PMID 39747003, 2025). "BC can be multifocal and exhibits pronounced intra- and intertumoral antigen heterogeneity, including variability in EGFR, Nectin-4 and TROP-2 expression, driven by genetic mutations, altered molecular pathways, and influences of the tumor microenvironment." (PMID 41471825, 2025). "Collectively, these data show that hypoxia-induced sustained EGFR activation endows tumor cells with drug resistance through STAT3-mediated induction of autophagy." (PMID 40940319, 2025). "Another mechanism of resistance is represented by the amplification of the MET proto-oncogene receptor tyrosine kinase (MET), which constitutes a key mechanism by which tumor cells can influence the blockage of the EGFR." (PMID 40002260, 2025). "In standard clinical practice, patients are selected for EGFR inhibitors based on RAS/BRAF mutation status and location of the primary tumor." (PMID 40982295, 2025). "A recent study compared non-covalent functionalization and pre-targeting strategies using anti-PEG x HER bsAbs, analyzing the biodistribution of luciferase mRNA-LNPs in mice bearing EGFR+ human tumor xenografts." (PMID 41250091, 2025). "Genetic testing identified an EGFR exon 19 deletion (L747-A750>P) and a low PD-L1 tumor proportion score (TPS, 0-10%)." (PMID 40051929, 2025). "No killing of Chinese hamster ovary (CHO) cells (B7-H6−/EGFR−) was observed, proving that killing capacities are restricted to the binding to EGFR-expressing cells indicating tumor target-specific redirection of NK cells." (PMID 39811682, 2025). "When bound to the extracellular domain of the EGFR, cetuximab blocks endogenous ligand binding, thereby inhibiting tumor cell proliferation and promoting cancer cell apoptosis." (PMID 41214390, 2025). "Their study revealed that targeting SRC and BRAF had an equivalent or better effect on tumor growth inhibition compared to targeting EGFR and BRAF, similar to our observations." (PMID 40481178, 2025). "As a result, the down-regulated EGFR in the tumour was identified as the direct effect of treatment." (PMID 40766212, 2025). "CAR-T therapies target tumor-associated antigens including KRAS G12D, mesothelin, EGFR, HER2, and CLDN18.2, with early trials reporting partial responses and stable disease." (PMID 40806185, 2025). "Epidermal growth factor receptor (EGFR) inhibitors normally block these pathways to suppress tumor growth." (PMID 40282985, 2025). "EGFR-positive tumor cells are recognized by CAR-T cells, leading to perforin and granzyme-mediated cell lysis." (PMID 40002679, 2025). "Current evidence shows that chemotherapy, PD-1 inhibitors and anti-EGFR/CD3 bispecific antibody have their corresponding anti-tumor efficacy." (PMID 41583476, 2025).
tumor (continued). "In conclusion, we reveal that agrin serves as a mechanosensing ECM protein for EGFR toward tumor stiffness." (PMID 40165020, 2025). "EGFR mutations were detected only in ISP‐SCCs (3/8, 37.5%), and one tumor was associated with HPV18." (PMID 39865501, 2025). "Nimotuzumab (also known as h-R3) is a humanized monoclonal antibody against EGFR, which has been proven to have essential anti-tumor functions both in vitro and in vivo by inhibiting proliferation, affecting angiogenesis, and promoting apoptosis." (PMID 40335598, 2025). "In colorectal cancer, long eccDNA carrying genes such as DHFR and EGFR induces the drug resistance in tumor cells; while in neuroblastoma, patients carrying MYCN-amplified eccDNA show an even lower survival rate." (PMID 40641599, 2025). "Among the most critical molecular targets in cancer therapy are Cyclin-Dependent Kinase 2 (CDK2), Epidermal Growth Factor Receptor (EGFR), and Tubulin, each of which plays a pivotal role in tumor progression and development of drug resistance." (PMID 40526618, 2025). "This probe enabled dual-modality imaging, integrating both fluorescence and radionuclide techniques, demonstrating the specific targeting of EGFR-positive tumor cells in an NCI-H460 xenograft model." (PMID 40906195, 2025). "Another study reported that the integration of the PRESSING panel with primary tumor sidedness provided further refinement in predicting response to first-line anti-EGFR therapy in mCRC." (PMID 40076838, 2025). "Preclinical studies have shown that activation of the EGFR pathway leads to the upregulation of immune checkpoint molecules such as PD-L1 on tumor cells, which consequently allows them to evade immune-mediated cytotoxicity." (PMID 41523436, 2025). "EGFR activation also leads to proliferation, angiogenesis, invasion, the inhibition of apoptosis, and metastasis in tumor cells via the activation of various signaling pathways." (PMID 40699639, 2025). "These advancements in EGFR-targeting peptides highlight their capability to inhibit tumor progression while minimizing off-target effects, paving the way for safer and more effective." (PMID 40428099, 2025). "SAB effectively suppressed collagen contraction, inhibited SCC-4 cell migration, alleviated oxidative stress, and downregulated the activity of profibrotic and tumor-associated pathways, including the TGF-β/Smad, EGFR, and MAPK signaling pathways." (PMID 41439141, 2025). "Target-antigen expression, e.g., EGFR expression, on normal urothelial or peri-tumoral cells raises the possibility of off-tumor conjugate binding, resulting in unintended tissue injury when PIT triggers cytotoxicity." (PMID 41471825, 2025). "The lncRNA CRNDE enhanced p300/YY1 binding to the EGFR promoter, leading to EGFR upregulation and resulting in enhanced tumor cell proliferation and sorafenib resistance." (PMID 40867514, 2025). "In pediatric gliomas, eccDNA carrying oncogenes such as EGFR and MYC is linked to tumor progression, resistance to radiation and chemotherapy, and enhanced tumor plasticity 24,47." (PMID 40521196, 2025). "Another study established that the exposure of tumor cells to radiofrequency electromagnetic radiation decreased EGFR levels and reduced cell viability, possibly through changes in electrostatic interactions and non-covalent binding." (PMID 40573248, 2025). "By inhibiting EGFR activity, therapies can potentially disrupt these critical processes, leading to reduced tumor growth and improved patient outcomes." (PMID 40149618, 2025). "An EGFR/HER2 dual-targeted inhibitor called pyrotinib has exhibited stronger tumor-suppressive effects in advanced LUAD patients carrying HER2 exon 20 mutations, closely related to its comprehensive inhibition of the HER2 signaling pathway." (PMID 40083325, 2025).